ENSG00000261459 (novel transcript)
Gene: Protein-coding gene on chromosome 16 (30,525,923 to 30,534,852, reverse strand). Ensembl gene ENSG00000261459.
Genetic constraint (gnomAD): Missense variants: 529 observed, 421.94 expected, observed/expected ratio (o/e) 1.25, 90% interval 1.17 to 1.35. Synonymous variants: 212 observed, 174.34 expected, observed/expected ratio (o/e) 1.22, 90% interval 1.09 to 1.36.